POSTN (periostin)
Diseases named in the same sentence as POSTN in open-access papers (continued):
Sharing a sentence is not in itself a finding about the gene and the disease.
asthma (continued). "In the field of asthma research, the role of periostin in relation to airway epithelial cells and fibroblasts has been of great interest, as well as its role in the pathogenesis of asthma caused by subcutaneous fibrosis." (PMID 25981515, 2015). "To date, there are limited data available regarding the levels and function of periostin in human asthma and in chronic obstructive pulmonary disease." (PMID 25981515, 2015). "This review will focus on what is known about periostin and its role in the pathophysiological mechanisms that mediate asthma." (PMID 25981515, 2015). "Taken together, these results show that periostin can be a useful biomarker to apply stratified medicine for SA and to yield better outcomes in asthma management." (PMID 26430389, 2015). "Periostin is involved in many aspects of asthma as well, including eosinophil recruitment, airway remodeling, development of a Th2 phenotype, and contributes to the increased expression of inflammatory mediators." (PMID 25981515, 2015). "There is a growing body of evidence regarding the role of periostin in asthma and type 2 inflammatory responses in particular." (PMID 24146092, 2014). "Biomarkers from both systemic (IgE, periostin, and circulating eosinophils) and airway (fractional exhaled nitric oxide (FeNO) and sputum eosinophils) sources are used in asthma research, especially among those with the allergic phenotype." (PMID 24891923, 2014). "Periostin expression is elevated in the bronchial epithelial cells of a subset of patients with asthma and is secreted basolaterally." (PMID 24146092, 2014). "Serum levels of periostin have been recognized as a potential biomarker in patients with non-small cell lung carcinoma and in patients with asthma." (PMID 24260297, 2013). "In asthma, the three-gene-mean of periostin, CLCA1 and serpinB2 correlated with FeNO (r = 0.75, p = 0.0002), blood eosinophils (r = 0.58, p = 0.003) and PC20 methacholine (r = -0.65, p = 0.0006), but not total serum IgE (r = 0.33, p = 0.1)." (PMID 23866775, 2013). "Epithelial cells from individuals with asthma produce high amounts of periostin, a cytokine that stimulates TGF-β production and modifies myofibroblast collagen synthesis." (PMID 24228254, 2013). "We anticipated that allergen challenge in mice would up-regulate periostin in the airway and model our previous findings in human asthma." (PMID 22093101, 2012). "Periostin promotes myofibroblast differentiation of palmar fascia mesenchymal cells and is a component of subepithelial fibrosis in asthma." (PMID 22363622, 2012). "Subepithelial periostin deposition and fibrosis are present in the bronchial tissue of both ovalbumin-sensitized and ovalbumin-inhaled mice and patients with asthma." (PMID 22363622, 2012). "Notably, increased levels of serum Periostin are consistently observed in conditions like asthma and other allergic diseases." (PMID 41001556, 2025). "Beyond diagnosis, periostin holds potential in guiding asthma phenotyping, helping identify patients with Th2-high inflammation who may benefit from targeted biologics (e.g., anti-IL-13 and anti-IL-4 receptor therapies)." (PMID 41374409, 2025). "Integrating periostin assessments with established biomarkers such as blood eosinophils and FeNO can advance comprehensive endotyping and patient stratification, supporting more personalized interventions in asthma management." (PMID 41374409, 2025). "Similarly, as periostin is known to play a role in the development of asthma, one of the aims of the study was to identify any potential relationship between periostin levels and the presence of GERD in children." (PMID 40981017, 2025). "However, the EXTRA trial found that other type 2 inflammatory biomarkers were predictive of omalizumab’s ability to reduce asthma exacerbations (blood eosinophils, FeNO, serum periostin)." (PMID 40863432, 2025). "Serum periostin levels were significantly higher in asthma patients compared with healthy controls." (PMID 41374409, 2025).
asthma (continued). "Taken together, FEO‐03, a formulation of essential oils, could ameliorate the fibrosis by inhibiting Th2‐specific cytokines and periostin derived epithelial‐mesenchymal transition in asthma." (PMID 40777200, 2025). "Receiver operating characteristic (ROC) curve analysis revealed that serum periostin > 45.88 pg/mL robustly discriminated asthma patients from controls with 94.1% sensitivity, 100% specificity, 100% positive predictive value, 89.3% negative predictive value, and an AUC of 0.987 (Figure 2A1)." (PMID 41374409, 2025). "Periostin expression is induced in airway epithelial cells by Th2 cytokines, particularly interleukin (IL)-4 and IL-13, pivotal mediators of type 2 inflammation in asthma." (PMID 41374409, 2025). "Importantly, serum periostin remained an independent predictor of asthma after adjusting for relevant confounders, including age, sex, and lung function metrics." (PMID 41374409, 2025). "The periostin-only model showed poor discrimination for predicting asthma severity (AUC = 0.56)." (PMID 41374409, 2025). "Notably, while pediatric data remain sparser, emerging studies confirm periostin’s relevance for asthma diagnosis and monitoring in children, including wheezing phenotypes and response to treatment." (PMID 41374409, 2025). "The association of the five genes CEACAM5, POSTN, TCN1, SCGB3A1, and CPA3 with asthma has been extensively identified and validated, and these are the most highly upregulated genes in patients with asthma, and CEACAM5 is associated with resting mast cells and eosinophils." (PMID 39963184, 2025). "These immunological markers may correspond to pathophysiological characteristics of asthma: periostin, IgE, IL-5, and IL-33 for T2 asthma; IL-6, IL-8, IL-17A, and IL-33 for non-T2 asthma." (PMID 38256660, 2024). "POSTN is a well-characterized biomarker and crucial asthma regulator." (PMID 38580753, 2024). "Indeed, the expression of periostin is increased in the airways of asthma patients and can be induced by IL-13/IL-4 in vitro." (PMID 38785953, 2024). "Among patients with CRSwNP, the expression of periostin is higher in the NPs of those with coexistent asthma than those without and is positively associated with levels of TSLP." (PMID 38690264, 2024). "The aim is to investigate whether asthma patients expressing low T2-activity, assessed by serum-periostin, blood-eosinophils, and FeNO can sustain their level of disease control during tapering of ICS." (PMID 37794472, 2023). "Similarly, 42 healthy control subjects and 20 previously ICS naïve patients with asthma who were treated with ICS exhibited decreases in serum periostin, correlating with increased FEV1%, decreased sputum eosinophils and decreased bronchial wall area." (PMID 40980110, 2023). "It has been also proposed that several T2 cytokines such as TSLP or periostin could be used as prognosis biomarkers for the development of asthma." (PMID 36694181, 2023). "Sputum periostin is worth considering as a phenotype-specific biomarker in asthma as its proximity to the airways may eliminate some of the confounding factors known to affect serum periostin." (PMID 36763690, 2023). "Pavlidis and colleagues report that serum periostin is a poor predictor of T2-high asthma as determined by epithelial transcriptomic profile, and discuss that their unpublished findings suggest sputum periostin may be more promising for this purpose." (PMID 36763690, 2023). "Serum periostin levels were slightly higher (ns) in patients with the T2 phenotype but strongly correlated to asthma endotypes, which may contribute to guide therapies targeting T2 cytokines in a more individualized fashion." (PMID 37744693, 2023). "Additionally, serum periostin is a useful biomarker for the management of severe asthma and can serve as a long-term predictive marker." (PMID 38203353, 2023). "Serum periostin levels according to asthma phenotypes and endotypes." (PMID 37744693, 2023).
asthma (continued). "Very briefly, the role of periostin, a matricellular protein, in asthma is believed to involve elevated production by structural cells in response to IL-13 secreted by activated T-helper 2 cells or type 2 innate lymphoid cells, which in turn can lead to increased airway fibrosis." (PMID 36763690, 2023). "From these results, we can conclude that serum periostin is increased in patients with asthma." (PMID 37629446, 2023). "Blood biomarkers, such as eosinophils and periostin, may be used to diagnose and manage asthma in the clinic." (PMID 37404842, 2023). "Furthermore, we were able to investigate relationships between sputum periostin and type 2 cytokines (IL-4 and IL-13) in a smaller, unrelated subset of 30 patients with asthma." (PMID 36763690, 2023). "CST1, POSTN, CPA3, and SERPINB2 were key genes that potentially linked AR and asthma." (PMID 36733482, 2023). "Several studies have evaluated omalizumab effectiveness in treating severe asthma; a randomized controlled trial discovered that severe asthma patients with high blood eosinophil counts, FeNO levels, and serum periostin experienced a significant reduction in exacerbation frequency." (PMID 38053108, 2023). "Neither the monomeric form, nor the cleaved product could be detected in sputum samples derived from three mild asthma patients (#1 - #3), compatible with the presence of very low levels of sputum periostin as measured by both Assay A and Assay B." (PMID 36763690, 2023). "In addition, biologics targeting IL-4/1L-13 (dupilumab) and IL-13 (i.e., lebrikizumab) have been shown to suppress serum periostin levels in asthma patients." (PMID 37108417, 2023). "Notably, PSES hypomethylate ALOX15, CAPN14, and POSTN asthma genes which increases the prevalence of asthma symptoms." (PMID 36960908, 2023). "Sputum periostin was detectable in 44% of all samples analyzed using Assay A, and 90% of all samples using Assay B. Positive detection levels were similar in the mild-to-moderate (43% assay A, 88% assay B) and severe asthma (45% assay A, 93% assay B) groups." (PMID 36763690, 2023). "The roles of periostin in asthma have been validated by many previous studies." (PMID 37241840, 2023). "One factor complicating the utility of circulating periostin as a biomarker in asthma may be that its levels are affected by periostin originating from sources outside the lung." (PMID 36763690, 2023). "Periostin is an extracellular matrix protein with an upregulated expression in airway epithelial cells and fibroblasts after activation by IL-13 and alarmin IL-33 in patients with some types of asthma and allergic inflammation, but also in pulmonary fibrosis." (PMID 40980110, 2023). "In conclusion, ICS treatment may be particularly beneficial for patients with asthma who have low or normal BMI, elevated sputum eosinophils and/or elevated periostin, and possibly elevated FeNO levels." (PMID 40980110, 2023). "The difficulty in obtaining standardized sputum samples is one of the drawbacks of the current investigation, and all others investigating sputum as a source of biomarkers in asthma, as it may affect the clinical utility of sputum periostin measurements." (PMID 36763690, 2023). "Furthermore, when patients were divided according to sputum inflammatory profile, only sputum periostin showed different levels among the four profiles being lowest in paucigranulocytic and highest in mixed granulocytic asthma." (PMID 36763690, 2023). "Periostin is a secreted protein that induces cell attachment and spreading; plays a role in cell adhesion; and its differential expression is known to regulate T2-high asthma, myocardial-infarction-regulating heparin binding and cell-adhesion molecule binding." (PMID 36360315, 2022). "The addition of dupilumab lowers serum periostin expression in AD, asthma, CRSwNP, and EE." (PMID 36611844, 2022). "In addition to POSTN (a known prognostic marker for asthma), FOSB can be observed to be upregulated in asthmatics." (PMID 35406434, 2022).
asthma (continued). "A logistic regression model, including sex, age, IgE levels, blood eosinophil numbers, body mass index, FeNo levels, and serum periostin levels, in 59 patients with severe asthma, showed that the serum periostin level was the best predictor of airway eosinophilia." (PMID 36078171, 2022). "Periostin is highly expressed in chronic inflammatory diseases, including asthma, allergic conjunctivitis, eosinophilic chronic sinusitis/chronic rhinosinusitis with nasal polyp, and atopic dermatitis, and periostin plays important roles in the pathogenesis of these diseases." (PMID 36359784, 2022). "Therefore, in this study, we aimed to characterize stable and exacerbation period peripheral blood cytokine and periostin levels of 5 different predefined severe asthma phenotypes with real-life data." (PMID 36326393, 2022). "SERPINB2 and POSTN are an epithelial gene signature for type 2‐high asthma." (PMID 35344278, 2022). "The role of periostin in asthma is still under investigation." (PMID 36078171, 2022). "Additionally, the production of POSTN is also upregulated in allergic rhinitis and aspirin-induced asthma." (PMID 35752781, 2022). "In addition to this, the effective therapeutic response of anti-IgE Ab omalizumab in asthma patients was dependent on high serum periostin." (PMID 36611844, 2022). "Both plasma periostin and saliva periostin levels had the advantage of early diagnosis of asthma." (PMID 36611844, 2022). "However, the results from this study warrant further investigation into the molecular mechanisms of the four genes (PPARD, STAT1, BCL3, and POSTN) in both asthma and lung cancer cell lines, independently and in combination." (PMID 35406434, 2022). "Periostin is highly expressed in chronic inflammatory diseases, including asthma, atopic dermatitis, chronic rhinosinusitis with nasal polyp, and allergic conjunctivitis, suggesting that periostin plays important roles in the pathogenesis of inflammatory diseases." (PMID 35707463, 2022). "Given the results from the network prediction and experimental evaluation, the down-regulation of POSTN/TGF-β by AEO treatment might be a key therapeutic target of asthma and lung fibrosis." (PMID 35335934, 2022). "Clarithromycin can alleviate asthma by arresting periostin generation." (PMID 36611844, 2022). "Moreover, for this reason, some studies have focused on periostin levels of exhaled breath condensate (EBC) in pediatric patients with asthma as a potential biomarker for the disease." (PMID 35327702, 2022). "Exhaled breath condensate (EBC) periostin levels seemed to reflect the emergence of CRS in asthma." (PMID 36611844, 2022). "Moreover, patients with high periostin levels were found to show reduced asthma exacerbations after treatment with lebrikizumab (anti-IL-13), demonstrating the prognostic value of serum periostin concentrations." (PMID 34658882, 2021). "POSTN is also highly expressed during chronic inflammatory diseases such as asthma, atopic dermatitis, eosinophilic chronic sinusitis/chronic rhinosinusitis with nasal polyps, and allergic conjunctivitis, and plays important roles in the pathogenesis of these diseases." (PMID 34513869, 2021). "Periostin is linked to eosinophil recruitment to inflamed airways in asthmatics and idiopathic pulmonary fibrosis (IPF) patients; serum periostin predicts airway eosinophils in steroid-resistant asthma, and predicts disease progression in IPF." (PMID 33671475, 2021). "Also of interest is the fact that the classical T2 sign (CCLA1, POSTN, and SERPINB2) was associated with the two kinds of asthma analyzed, which is consistent with our previous published data." (PMID 33936056, 2021). "Periostin is indeed one of the most highly expressed genes in asthma." (PMID 34512647, 2021). "Additionally, periostin, a marker for asthma responses in the lung, was also decreased following IL-13 neutralization (data not shown), suggesting the neutralization of IL-13 was affecting typical downstream pathways." (PMID 34185704, 2021).